SPARC (secreted protein acidic and cysteine rich)
Diseases named in the same sentence as SPARC in open-access papers (continued):
Sharing a sentence is not in itself a finding about the gene and the disease.
cancer (continued). "Therefore, the function of SPARC in oncogenesis is somewhat controversial and it cannot be determined based only on the endogenous expression of SPARC in cancer cells." (PMID 33579227, 2021). "Furthermore, in addition to such metabolic implications, SPARC is also involved in other growth and homeostasis-related patterns, including cancer homeostasis." (PMID 33435573, 2021). "Plus, discovering a novel targeted nanoparticle and enhanced drug delivery system using SPARC could improve the pharmacologic and therapeutic properties of conventional cancer treatment for patients with PC." (PMID 34336679, 2021). "SPARC is overexpressed during cancer and has been reported to have anti-cancer properties." (PMID 33435573, 2021). "SPARC expression in cancer cells enhanced their migration and invasion on FN1-coated dishes." (PMID 33579227, 2021). "Various functions of SPARC in cancer cells have been reported." (PMID 33579227, 2021). "One of the SPARC properties is its ability to optimize the regeneration environment with an improved cellular regenerative capacity from different perspectives (metabolics, tissue repair, oxidation, inflammation, cancer, etc.), as illustrated below." (PMID 33435573, 2021). "The established myokines IL6, irisin and SPARC have cancer-protective functions." (PMID 34359731, 2021). "However, the role of SPARC in cancer research has been the subject of controversy and appears to be context and tissue-dependent." (PMID 34205668, 2021). "And moreover, the functions of SPARC in different cancers are controversial." (PMID 34912848, 2021). "Averaging these scores across cancer types/subtypes identified many ESGs that are strongly and consistently associated with the CAF signatures, including classical CAF markers such as FAP, SPARC, THY1 (CD90) and various collagens." (PMID 33972543, 2021). "The result may explain why larger amounts of stromal tissues were reported to accompany SPARC-expressing cancer cells in vivo." (PMID 33579227, 2021). "Moreover, Chen YL and his colleagues also found that the expression level of SPARC was 5.78-fold higher in cancer tissues, and high SPARC expression in ESCC parenchyma was related to lymph node metastasis and poor prognosis." (PMID 31897236, 2020). "SPARC, which is increased by aerobic exercise, has potential as a cancer treatment." (PMID 33019579, 2020). "Interestingly, an IPA analysis showed that different regulated genes were positively associated with the invasion and migration process in cancer cells: VCAN, SPARC, IL6, MMP14, IL4R, ICAM, TIMP1 and IGF2." (PMID 32848147, 2020). "The SPARC (secreted protein acid and rich in cysteine) protein plays a central role in cancer metastasis through controlling extracellular matrix (ECM) synthesis and turnover, cell-matrix interaction and remodeling, changing of cell shape, proliferation, migration and angiogenesis." (PMID 32580473, 2020). "Next, we pooled all the 20 cancer types and found that all the three markers were prognosticator of solid cancers (SPARC: HR = 1.10, 95% CI = [1.01, 1.20], p = 0.028; SPP1: HR = 1.25, 95% CI = [1.14, 1.36], p < 0.001; BGLAP: HR = 1.13, 95% CI = [1.04, 1.24], p = 0.005)." (PMID 33240930, 2020). "Several studies have shown that the mRNA and protein levels of SPARC were higher in cancer tissues compared with the corresponding adjacent normal epithelium in ESCC, and were significantly associated with local invasion, distant metastasis and poor prognosis 14-16." (PMID 31897236, 2020). "However, few clinical studies have examined the relationship between serum SPARC levels after surgery and the survival of patients with cancer." (PMID 32512862, 2020). "SPARC was mainly expressed in GCAFs (47.4%) and was rarely expressed in cancer cells (11.5%)." (PMID 31139014, 2019). "In human tumors, SPARC could alter the activity of cancer cells, modulating cell growth, apoptosis, adhesion migration, and invasion." (PMID 31297369, 2019).
cancer (continued). "Moreover, in vitro co-culture models using CRC cell lines together with colon-associated fibroblasts were established to determine the effect of fibroblast-derived SPARC on cancer cells." (PMID 31554208, 2019). "In fact, the relative expression level of GRP78 to SPARC in CRC cells may determine the level of chemosensitivity of cancer cells to drug therapy." (PMID 31243264, 2019). "Importantly, when these adipocytes are challenged by OvCa cells, SPARC suppresses their interaction with cancer cells and consequently inhibits the acquisition of CAA phenotype that fosters OvCa omental dissemination and colonization." (PMID 30765860, 2019). "Our findings suggest that SPARC may play a key role in coordinating ER stress response, and autophagy signaling in cancer cells to facilitate a more favorable response to chemotherapy." (PMID 31243264, 2019). "SPARC was mainly expressed in GCAFs and was rarely expressed in cancer cells." (PMID 31139014, 2019). "One is extracellular SPARC mediated pathway, which might rely on the rapid exchanged of lipidic components 27, and the other is cancer cell membrane SPARC mediated pathway, which is receptor-mediated endocytosis." (PMID 31695779, 2019). "We examined SPARC mRNA and protein expression in various cancer cell lines." (PMID 31695779, 2019). "Furthermore, we investigated the correlations between clinicopathological features and both GCAF-derived SPARC and cancer cell-derived SPARC." (PMID 31139014, 2019). "Furthermore, it demonstrates that it is the relative expression level of GRP78 to SPARC that influences the survival of cancer cells in response to chemotherapy." (PMID 31243264, 2019). "In addition, we observed up-regulation of secreted protein acidic and rich in cysteine (SPARC), which has been reported to be inactivated by promoter methylation in cancer." (PMID 30925862, 2019). "The mechanisms by which SPARC influences cancer cells’ response to chemotherapy appears complex." (PMID 31243264, 2019). "However, most evidence supporting the role of SPARC in solid tumours is based on cancer cell-derived SPARC." (PMID 31139014, 2019). "More SPARC positive cells were located in the stroma adjacent to the cancer nest." (PMID 29156791, 2017). "Stromal cells-expressing SPARC also regulate the behavior of cancer cells and prognosis." (PMID 28718842, 2017). "The authors identified that SPARC restrains urothelial carcinogenesis, progression and metastasis through an effect on cancer cells inhibiting carcinogen-induced cell cycle deregulation and on stromal cell plasticity, inhibiting their acquisition of a pro-inflammatory cancer associated phenotype." (PMID 28915710, 2017). "In highly metastatic cancer, SPARC promotes migration and EMT." (PMID 28969021, 2017). "The role of SPARC has been studied in different types of cancer." (PMID 28505082, 2017). "All of these indicated that SPARC played an important role in cancers." (PMID 29262657, 2017). "The interaction of SPARC between different cancers and their microenvironments might be an interesting subject for further investigation." (PMID 28969021, 2017). "Therefore, our future research would focus on the relationship of SPARC with 5-FU and other chemotherapy drugs in various cancers." (PMID 28053291, 2016). "An increasing number of studies have shown altered SPARC expression in various types of cancer." (PMID 27421134, 2016). "We and some other scientists have demonstrated that SPARC in cancer cells could regulate the apoptosis, prohibit the angiogenesis and promote the invasion and the proliferation of tumors." (PMID 28053291, 2016). "Clinically, SPARC has been uncovered as the potential prognostic marker in several cancer types." (PMID 28053291, 2016). "The prognostic and predictive potential of SPARC in cancer is controversial." (PMID 27544129, 2016). "SPARC is overexpressed in many types of human cancers and is a marker of poor prognosis." (PMID 26926673, 2016).
cancer (continued). "The reasons for these disparate results, even within the same type of cancer, are unknown but may be explained by different methodologies used to assess SPARC expression as well as its complex biology." (PMID 27544129, 2016). "The contradictory findings in these studies underline that further research is needed to clarify whether, and in which cancer types, SPARC expression may be a valuable tool to predict response to nab-paclitaxel." (PMID 27411683, 2016). "Interestingly, both normal and cancer cells elicit growth inhibition when exposed to extracellular-derived SPARC, but only cancer cells undergo increased apoptosis." (PMID 27622658, 2016). "SPARC was mainly localized in the cytoplasm of primary cancer." (PMID 25859409, 2015). "Possible explanations may include that chemotherapy may “enrich” to the SPARC-positive GC cells, then kill the SPARC-overexpressioning GC cells or chemotherapy may contribute to the cancer cells inner genetic and phenotypic change in cancer cells." (PMID 25859409, 2015). "Interestingly, SPARC is overexpressed in several aggressive cancers and downregulation of SPARC expression decreases cancer cell invasion and survival." (PMID 25890381, 2015). "SPARC has a wide tissue distribution and is found not only in the connective tissue stroma of solid organs but is also expressed in macrophages at the sites of wound repair and cancer." (PMID 26656750, 2015). "Even though SPARC has been implicated in tumorigenesis, the specific SPARC-mediated mechanisms involved in cancer have not been definitively elucidated, likely due to the diversity of SPARC functions." (PMID 24484617, 2014). "SPARC expression patterns appear to correspond with different outcomes in different cancer types." (PMID 24484617, 2014). "Since many similarities can be observed between invasive extravilloustrophoblast cells and cancer cells, we hypothesized that SPARC might also be involved in the invasion process of EVT cells." (PMID 23935929, 2013). "SPARC promotes the proliferation of stromal cells while inhibiting cancer cells." (PMID 22481923, 2012). "We found that SPARC diffused from the stroma to cancer domains." (PMID 22879971, 2012). "The disparate effect of SPARC is also evident between stromal fibroblasts and cancer cells." (PMID 22481923, 2012). "Recent studies show that SPARC modulates proliferation, apoptosis, invasion and angiogenesis in different types of cancer cells, however, the role of SPARC in tumourigenesis is complicated and seems to be cell-type specific owing to its diverse functions in a given micro-environment." (PMID 22957090, 2012). "AJCC disease staging is based on histological evidence of infiltration and metastasis, it was, therefore, hypothesised that SPARC and FOXP3 expression may be associated with primary CRC disease stage and cancer specific survival." (PMID 21818290, 2011). "The SPARC promoter has been shown previously to be modulated by DNA methylation in cancer." (PMID 21867537, 2011). "Interestingly, fenretinide [N-4(hydroxyphenyl) retinamide, 4-HPR], a synthetic retinoid with anti-cancer properties, was found to up-regulate the transcription, expression and secretion of SPARC via induction of the Brg-1 in a dose-dependent manner." (PMID 20687958, 2010). "Many types of cancers are characterized by upregulated expression of SPARC." (PMID 20525171, 2010). "Through the description of testable candidates and the experimental validation of a number of UTR-SNPs discovered on the secreted protein acidic and rich in cysteine (SPARC) gene, this report illustrates the utility of a cross-talk between in silico transcriptomics and cancer genetics." (PMID 17201911, 2007). "In contrast to cancer cells, stromal fibroblasts were frequently and strongly reactive for SPARC." (PMID 17187659, 2006). "The cellular origin of SPARC is variable among malignant tumours." (PMID 15558074, 2004).
cancer (continued). "Quantitation of SPARC mRNA expression might be a novel biomarker for the detection of cancer in patients with BE." (PMID 14562024, 2003). "In summary, these data suggest that upregulation of SPARC mRNA expression is an early event in Barrett's multistage disease, which already occurs at the level of IM and further increases during progression to cancer." (PMID 14562024, 2003). "Similarly, SPARC, although contributing to the invasive and metastatic properties of cancer cells, may also exhibit reduced expression in liver metastases due to the minimal stromal content in liver tissue." (PMID 40806530, 2025). "Some of the blood transport plasma proteins can also be uptaken by cancer cells via active targeting: cancer cells can selectively accumulate human serum albumin and transferrin because of the high expression levels of albumin-binding proteins (gp60 and SPARC) and transferrin receptors." (PMID 37299673, 2023). "Thus, both the surface modification of E. coli and expression of SPARC in the cancer cells, could alter the targeting and adhesion abilities of E. coli." (PMID 37062822, 2023). "Interestingly, further clinical exploration found that SPARC could be used as a candidate aim for the control of cancer." (PMID 37577749, 2023). "Myocines produced by active muscles like oncostatin M, irisin, and SPARC can directly downregulate cancer growth by impacting cell proliferation, stemness, apoptosis, drug resistance, metabolic remodeling, and the epithelial–mesenchymal tissue transformation of cancer cells." (PMID 37958310, 2023). "Moreover, SPARC and decorin might exert an anticancer effect by decreasing cancer cell proliferation, limiting migration and increasing apoptosis." (PMID 37533033, 2023). "More specifically, myokines could be divided into those that may directly influence the TME, such as secreted protein rich in cysteine (SPARC), oncostatin M, and irisin; and those that may indirectly affect cancer evolution by enhancing the antitumor immune response, such as IL-6, IL-7, and IL-15." (PMID 35454797, 2022). "We focused on secreted protein acidic and cysteine rich (SPARC), a potential cancer-invasion marker, and assessed whether the super-resolution method could facilitate biological interpretations provided by pathologists based on histology patterns in H&E-stained images." (PMID 35260632, 2022). "This evidence, together with our findings in the wound healing assay showing that integrin αvβ3 and ZEB1 mediate SPARC-induced migration, suggests that SPARC and some integrin genes could be positively and reciprocally regulated, contributing to the migration and invasion of cancer cells." (PMID 35682554, 2022). "Therefore, modulation of SPARC’s gene expression may lead us to harness the countermeasures necessary to protect the CNS of the astronauts from neurodegeneration and cancer during and after space flight." (PMID 36430810, 2022). "However, SPARC expression provides different outcomes depending on the cancer type and its stages." (PMID 35965624, 2022). "Furthermore, considering our results that SPARC is a survival stratification marker of pStage II/III GC after curative surgery at both the gene and protein levels, SPARC expression may be related to cancer infiltration and metastasis." (PMID 36139587, 2022). "In addition, SPARC drives cancer EMT by modulating TME immune cells." (PMID 34131655, 2021). "Therefore, SPARC expression in fibroblasts may support cancer progression, despite its apparent antiproliferative effects in cancer cells." (PMID 33534863, 2021). "However, SPARC has gained attention as a myokine because of its cancer-suppressing effects." (PMID 33019579, 2020). "Therefore, it was necessary to identify HSA and SPARC interactions in cancer cells." (PMID 31695779, 2019). "Therefore, SPARC may play different roles in different cancers and in different development stages of the same cancer." (PMID 29921304, 2018).
cancer (continued). "Together our data suggests that SPARC expression must be tightly regulated to maintain ECM in a growing tissue, and that therapeutic strategies buffering SPARC activity to within the optimal range for BM collagen assembly may limit cell invasion during cancer metastasis." (PMID 26926673, 2016). "Moreover, loss of SPARC in mesothelial cell-derived ECM has a negative impact on paclitaxel-induced cancer cell death." (PMID 27622658, 2016). "Moreover, the difference of primer sequence, antibody, and the cut off value selected might result in the different features of SPARC detection, such as the positive rate of 50%–72% and the histological location in stroma/cancer cells." (PMID 28053291, 2016). "In addition, data mining results from The Comparative Toxicogenomics Database indicates that bisphosphonate down-regulates expression of LOX, MMP2, COL1A1 and SPARC, which means bisphosphonate may suppress cancer metastasis by targeting these four genes." (PMID 27147578, 2016). "In addition, many types of cancers are characterized by the upregulated expression of SPARC." (PMID 23516489, 2013). "Therefore, the function of SPARC in cancer merits further investigation." (PMID 22879971, 2012). "On the other hand, some articles found that SPARC may promote apoptosis in cancer cells." (PMID 20525171, 2010). "In cancer, SPARC may exert divergent actions reflecting the complexity of this protein." (PMID 19920824, 2010). "We next assessed CRAd's CPE on SPARC-positive large T antigen-transformed microendothelial cells (HMEC-1) and WI-38-fetal lung fibroblasts that could be considered as resembling the potential characteristics of cancer-associated stromal cells." (PMID 19337591, 2009). "In addition, the decreased expression of FOXM1 and SPARC in liver metastases compared to primary tumors may mainly reflect the phenotypic changes associated with metastatic progression rather than other cancer antigens." (PMID 40806530, 2025). "Regarding cancer antigens, our findings highlight the expression of FOXM1 and SPARC as being significantly lower in liver metastases than in primary CRC." (PMID 40806530, 2025). "Our most important finding is a possible involvement of Notch-2 and its signalling pathway (dynamin-2, nicastrin, SPARC and PROS1) in dormancy of cancer spheroids in a HMW-HA concentration (5 wt%) representative of normal brain ECM." (PMID 40881990, 2025). "There are over 600 myokines in human myocyte-conditioned medium, including myostatin, IL-6, IL-15, irisin, myonectin, decorin, SPARC and FSTL-1, some of which are involved in cancer suppression." (PMID 41300368, 2025). "The upregulation of SPARC, MMP9 and ITGA5 in OSF and OSCC indicates their role in the induction of fibrosis and progression to cancer." (PMID 39865173, 2025). "Genes implicated in extracellular matrix interactions and tissue remodeling, such as SPARC and FAP, frequently contribute to tissue development, repair, and the cancer microenvironment." (PMID 39336798, 2024). "SPARC+ T cells highly expressed the genes responsible for extracellular matrix formation, SPARC, VEGFA, A2M and COL4A126, thus implicating an important role in cancer development and metastasis." (PMID 37550396, 2023). "Correspondingly, in SW620 cells, IM12 led to cytosolic-nuclear shuttling, activation of global DNA demethylation, suppression of CRC cancer cell growth and enhanced expression of RORA and SPARC." (PMID 37620362, 2023). "In SW480 cells, IWR1 treatment resulted in the translocation of Tet2CD from the nucleus to the cytosol, impaired TET2-induced DNA demethylation, facilitated the growth of cancer cells and decreased the expression of RORA and SPARC." (PMID 37620362, 2023). "The SPARC/osteonectin, CWCV and Kazal-like domains proteoglycan 1 (SPOCK1) is a proteoglycan which is involved in many types of cancer, including RCC." (PMID 37370817, 2023).